ADAMTS7 (ADAM metallopeptidase with thrombospondin type 1 motif 7)
Diseases named in the same sentence as ADAMTS7 in open-access papers (continued):
Sharing a sentence is not in itself a finding about the gene and the disease.
atrial fibrillation (1 paper, 2025). A disorder characterized by an electrocardiographic finding of a supraventricular arrhythmia characterized by the replacement of consistent P waves by rapid oscillations or fibrillatory waves that vary in size, shape and timing and are accompanied by an irregular ventricular response. "The primary aim of our study is to follow the effect of DOAC (rivaroxaban, apixaban or dabigatran) treatment over time on ADAMTS7 promoter methylation in newly diagnosed non-valvular atrial fibrillation (AF) patients, both in pooled analysis as well as stratified in bleeding cases and controls." (PMID 40565590, 2025).
bladder cancer (1 paper, 2013). "Here, we report that the 190 kDa gelatinase (ADAMTS-7) was detected in the urine of a little number of bladder cancer patients (26%)." (PMID 23672427, 2013). "Taken together, our study detected many species of gelatinases in the urine of bladder cancer patients with primary tumor (both bilharzial and non bilharzial) including MMP-2, MMP-9, MMP-9 dimer, MMP-9/NGAL, MMP-9/TIMP-1 and ADAMTS-7." (PMID 23672427, 2013).
breast carcinoma (1 paper, 2015). "ADAMTS-7 expression had been found in urine from patients with prostate, bladder, and breast cancer, suggesting a diagnostic and prognostic role of ADAMTS-7 in the detection and therapeutic value in tumor growth, invasion, and metastasis." (PMID 26696755, 2015).
coronary artery calcification (1 paper, 2019). Calcification of the coronary artery, used as a measure of coronary atherosclerosis, a risk factor for myocardial infarction. "However, Hispanics enrolled in the MESA (Multi-Ethnic Study of Atherosclerosis) cohort, were found to have various ADAMTS7 SNPs related to coronary artery calcification, without impact on CIMT." (PMID 31460868, 2019).
depression (1 paper, 2026). "Based on the Fisher Combined Test, only THRAP3 (p = 3.0 × 10-2) and ADAMTS7 (p = 2 × 10-2) were jointly significant for depression (BDI-II) and AST, ALT, AST/ALT ratio, FAST, and CAP (kPa)." (PMID 41898876, 2026). "Two genes, ADAMTS7 and THRAP3, warrant further investigation as potential targets for therapeutic interventions to manage MASLD and depression among Mexican Americans." (PMID 41898876, 2026).
disc degeneration (1 paper, 2024). "In contrast, the rupture of annulus fibrosus during the later stages of disc degeneration, providing a patent route for releasing higher levels of COMP/ADAMTS7 into blood." (PMID 38528617, 2024).
endothelial dysfunction (1 paper, 2023). In vascular diseases, endothelial dysfunction is a systemic pathological state of the endothelium (the inner lining of blood vessels) and can be broadly defined as an imbalance between vasodilating and vasoconstricting substances produced by (or acting on) the endothelium. "AIDA, ARHGEF26, ADAMTS7), most are implicated in endothelial dysfunction for the first time." (PMID 36928188, 2023).
femoral neck fracture (1 paper, 2015). Fractures of the short, constricted portion of the thigh bone between the femur head and the trochanters. "In this study we compared the expression of ADAMTS-7, TNF-α, and Phospho-NF-κB in patients with femoral neck fracture (FNF) and osteonecrosis of femoral head (ONFH) at different stages." (PMID 25653475, 2015).
gastric cancer (1 paper, 2025). A primary or metastatic malignant neoplasm involving the stomach. "Among the 19 ADAMTS family members, our research focused on ADAMTS7, which exhibited significant overexpression in gastric cancer (GC)." (PMID 39781347, 2025).
glioma (1 paper, 2022). A benign or malignant brain and spinal cord tumor that arises from glial cells (astrocytes, oligodendrocytes, ependymal cells). "Among them, ADAM9, ADAM12, ADAMTS7, ADAMTS9, and ADAMDEC1 were the proteases where increased expression associated with poorer prognosis of glioma patients." (PMID 36172139, 2022).
ischaemic stroke (1 paper, 2019). "However, the link between ADAMTS7 variability and ischaemic stroke (IS) has yet to be determined." (PMID 31460868, 2019).
liver cancer (1 paper, 2020). An epithelial or non-epithelial malignant neoplasm that arises from the liver. "Among the genetic mutations in liver cancer, the Asian ADAMTS7 mutation is only found in Asian Americans." (PMID 32884571, 2020).
lymph node metastasis (1 paper, 2025). "Results showed a statistically significant correlation between ADAMTS7 expression and lymph node metastasis (P = 0.011), TNM stage (P = 0.036), and infiltration depth (P = 0.001)." (PMID 39781347, 2025).
osteonecrosis (1 paper, 2015). A none disease characterized by death of bone tissue due to a lack of blood supply. "Level of ADAMTS-7 is elevated in articular cartilage of osteonecrosis of femoral head; ADMATS-7 is positively associated with TNF-α and NF-κB." (PMID 25653475, 2015).
psoriasis (1 paper, 2023). An autoimmune condition characterized by red, well-delineated plaques with silvery scales that are usually on the extensor surfaces and scalp. "Following this, knowing that IL-6 is an NFκB-dependent cytokine associated with ADAMTS7 production, we assessed this association and found a positive correlation in psoriasis." (PMID 36677041, 2023).
ventricular dilatation (1 paper, 2018). "Thus, ADAMTS-7 may change ECM components and promote ventricular dilatation by promoting COMP degradation in cardiac fibroblasts." (PMID 29523183, 2018).
tumor (9 papers, 2015 to 2025). "ADAMTS7 is a cartilage oligomeric matrix protein-cleaving enzyme involved in extracellular matrix remodeling, whose family members are also linked to tumor progression by affecting the interplay between the malignant cells and local microenvironment." (PMID 40873563, 2025). "Our own analysis showed also increased expression of ADAMTS7, 14 and 18 in tumors compared with adjacent non tumor tissues and high expression in tumors was associated with worse prognosis." (PMID 33805340, 2021). "The mutation frequencies of FAM83B, ZNF585A, DMBT1, ACACA, NOVA1, PCTH1, and ADAMTS7 were significantly higher in the high‐risk group, suggesting that these mutations may contribute to tumor development." (PMID 35616307, 2023). "In a mouse peritoneal metastasis model, the Sh-ADAMTS7#2 group showed significantly fewer intraperitoneal metastatic nodules, highlighting the role of ADAMTS7 in promoting tumor proliferation and metastasis in GC development." (PMID 39781347, 2025). "Tumor growth in the Sh-ADAMTS7#2 group was significantly slower, with notable reductions in both size and volume over time, as well as a marked decrease in final tumor weight compared to the control group." (PMID 39781347, 2025). "The results demonstrated a significant elevation in ADAMTS7 expression in tumour tissues relative to paracancerous tissues." (PMID 39781347, 2025). "Experiments showed that silencing the ADAMTS7 gene significantly inhibited tumor cell proliferation and metastasis." (PMID 39781347, 2025). "In accordance with this observation, the pro-tumor role of ADAMTS7 was recently supported by its identification in a signature of cancer stem cells that contribute to the development and therapeutic resistance of HCC." (PMID 33805340, 2021). "The reduced expression of ADAMTS7 in OS raised intriguing questions regarding its role in OS tumor biology." (PMID 32692461, 2020). "To investigate whether ADAMTS7 also acts in vivo, we constructed xenograft tumor models using nude mice." (PMID 39781347, 2025). "This independence indicates that ADAMTS7 may serve as a specific marker for invasive behavior in GC, without being influenced by broader patient characteristics or disease stage, highlighting its potential clinical significance in assessing tumor aggressiveness." (PMID 39781347, 2025). "Transwell and scratch assays showed that the negative effect of ADAMTS7 knockdown on tumor cell migration was neutralized by the administration of HY-134476 reagents." (PMID 39781347, 2025). "We observed genetic heterogeneity also in spheroids for several genes, as indicated by low SNV frequencies, for instance, in ADAMTS7, CSMD3, ERN1, FAT3, and RAD51C/D, supporting the view that tumor lesions are composed of mixed tumor cell populations with varying frequencies of SNVs." (PMID 32533757, 2020). "The matrix metallopeptidase ADAMTS7 expressed in FS was the only member of this gene family found among the top 25 most significantly upregulated genes in STS examined in this study, and this family of proteins is known for their promotion of tumor cell invasion and metastasis." (PMID 36099287, 2022).
cardiovascular disease (6 papers, 2021 to 2025). "The detrimental role exerted by ADAMTS-7 in cardiovascular diseases has been corroborated by in vivo models." (PMID 34587841, 2021). "ADAMTS7 is a well-known enzyme assessed as for its role in cardiovascular disease pathogenesis." (PMID 40565590, 2025). "In contrast to our findings, others failed to observe an association between the ADAMTS7 rs3825807 polymorphism and cardiovascular disease." (PMID 36833435, 2023). "The absence of any significant association between ADAMTS-7 levels and diastolic dysfunction can be considered surprising, taking into account that the role of ADAMTS-7 in cardiovascular disease has been established in both preclinical and clinical models." (PMID 39768861, 2024).
cancer (5 papers, 2013 to 2025). A tumor composed of atypical neoplastic, often pleomorphic cells that invade other tissues. "The remaining gene mutations were all PGCA specific, among which ADAMTS7 mutations were found associated with oncogenesis and dismal prognosis in a variety of cancers." (PMID 40873563, 2025). "The presence of different MMPs including HMWs (MMP9-dimer, MMP9-TIMP-1, ADAMTS-7) was reported in the urine of a variety of cancer patients including bladder." (PMID 23672427, 2013). "Each MMP was detected at significantly higher rate in urine from cancer patients compared to control subjects except in MMP-9/TIMP-1 and ADAMTS-7." (PMID 23672427, 2013). "The other three differentially mutated genes, including SAGE1, TRPM3, and ADAMTS7, have not been implicated in HCC, but in some other cancers." (PMID 27246981, 2016).
heart diseases (1 paper, 2015). "Further studies are necessary to assess the mechanisms of ADAMTS-7 in ventricular remodeling and heart diseases." (PMID 25885961, 2015).
infection (1 paper, 2012). The state of being infected such as from the introduction of a foreign agent such as serum, vaccine, antigenic substance or organism. "Interestingly, RNAi of DPP3 using siDPP3 significantly (p<0.05) increased CRE/CREB activation under mock-infected conditions despite DPP3 not being implicated in the CRE/CREB pathway, and silencing of ADAMTS7 significantly (p<0.05) abrogated CRE/CREB activation during infection." (PMID 22606348, 2012).
vascular disorder (1 paper, 2015). A general term used to describe any disease affecting blood vessels]. "In conclusion, ADAMTS-7 is involved in the pathogenesis of vascular disorders through degradation of COMP matrix and TSP-1, accelerated migration and proliferation of VSMCs, and regulation of inflammatory cytokines." (PMID 26696755, 2015).
ADAMTS7 also shares sentences with these, for which no sentence is quoted: pulmonary arterial hypertension (2 papers); brain ischemia (1); cardiomyopathy (1); cerebral arterial (1); chronic kidney disease (1); degenerative diseases (1); dilated cardiomyopathy (1); dyslipidemia (1); endometriosis (1); hyperlipidemia (1); inflammation (1); Insulin resistance (1); left ventricular hypertrophy (1); Obesity (1); osteonecrosis of femoral head (1); osteosarcoma (1); pneumonia (1); rheumatic diseases (1); Sepsis (1); thrombotic thrombocytopenic purpura (1); transient ischemic attack (1); upper respiratory infections (1).